NLRP12 (NLR family pyrin domain containing 12)
Diseases named in the same sentence as NLRP12 in open-access papers (continued):
Sharing a sentence is not in itself a finding about the gene and the disease.
tumor (continued). "Similar to that seen in the DEN model, DEN plus CCl4-treated Nlrp12-/- mice developed a greater tumor burden with significantly larger tumors than WT mice." (PMID 30990169, 2019). "Antibiotic-treated Nlrp12-/- mice exhibited a profound reduction of tumor burden and expression of AFP after DEN-induced tumorigenesis." (PMID 30990169, 2019). "In addition, analysis of tumor tissues revealed that NLRP12 promoted HK2 expression, histone lactylation, H3K18la, lactate levels and Myc transcription in vivo, all of which were reversed by sh-HK2 intervention." (PMID 40796546, 2025). "There were also reports showing that NLRP12 was a tumor suppressor gene." (PMID 39076995, 2024). "Finally, a xenograft mouse model was applied; the tumor volume and weight were determined, and NLRP12, p-IκBb-α, and p-IκBb-α expressions were evaluated using qPCR and Western blot." (PMID 37658975, 2023). "Furthermore, the expression of EMT genes and oncogenes, including Mmp3, Mmp7, Mmp8, Fn1, Vim, Foxc2, Ctnnb1, Lgr5, Axin2, cMyc, Ccnd1, and Yap1, was significantly high in the tumor of cohoused Nlrp12–/– compared with WT mice." (PMID 37581937, 2023). "Hyperinflammatory responses at the early stages of tumorigenesis may also lead to a higher tumor burden in Nlrp12–/– mice." (PMID 37581937, 2023). "To further examine whether the gut microbiota of Nlrp12–/– mice is tumor promoting, we performed a fecal transplantation study in which fecal microbiota from WT or Nlrp12–/– mice were transplanted into germ-free mice." (PMID 37581937, 2023). "There was increased expression of pro-proliferative and tumor promoting genes such as Ccnb1, Ccnd1, Survivin, and Myc, while the expression of Cdkn1a, an inhibitor of cell cycle progression, was significantly reduced in Nlrp12-/- HCC." (PMID 30990169, 2019). "Alpha-fetoprotein (AFP), a marker of HCC, was significantly higher in Nlrp12-/- tumor tissue." (PMID 30990169, 2019). "Our data suggest that within PML‐deficient and HCV‐transgenic mice, NLRP12 is downregulated in tumor tissue on an RNA level, but not on a posttranscriptional level." (PMID 31144474, 2019). "Nlrp12−/− mice exhibited an increase in tumor numbers in the AOM-DSS CAC model." (PMID 24273542, 2013). "Nlrp12−/− mice exhibited increased inflammation and tumor numbers." (PMID 24273542, 2013). "Moreover, decreased NLRP12 expression promoted the tumor size and weight in vivo." (PMID 37658975, 2023). "We hypothesized that JNK activation in Nlrp12-/- HCC occurs in parenchymal tumor cells." (PMID 30990169, 2019). "Indeed, enhanced LPS-induced canonical NF-κB activation was exhibited in Nlrp12−/− macrophages ex vivo, suggesting that microbial sensing and negative regulation of inflammation may account for NLRP12-mediated tumor suppression." (PMID 25071785, 2014). "NLRP12 encodes a protein that is a negative regulator of non-canonical NF-κB signaling, indicating that mutations in this gene may stimulate the NF-κB pathway and contribute to tumor formation." (PMID 40446009, 2025). "Thus, higher apoptotic death of hepatocytes following administration of DEN in the Nlrp12-/- liver was due to extrinsic factors, such as higher abundance of reactive oxygen and nitrogen species, cytotoxic cytokines (e.g., TNFα), and proapoptotic molecules in the tumor microenvironment." (PMID 31941025, 2020). "Consistent with reduced NLRP12 and higher β-catenin, the expression of Wnt target genes was upregulated in tumor tissue compared with nontumor tissue." (PMID 37581937, 2023). "Our data show reduced NLRP12 expression in Ep-CAM+ epithelial cells of tumor tissue compared with those of nontumor tissue." (PMID 37581937, 2023). "The link between NLRP12 and colorectal tumorigenesis was further evidenced by its expression profile in tumor and no-tumor tissue." (PMID 37581937, 2023).
tumor (continued). "We observed that approximately 30% of Nlrp12–/– mice developed invasive adenocarcinoma, while none of the wild-type (WT) mice showed tumor invasiveness at the same time, suggesting a critical role for NLRP12 in CRC progression and invasion." (PMID 37581937, 2023). "Consistent with reduced expression of NLRP12 in WT tumor, there was increased activation of β-catenin accompanied by higher phosphorylation of GSK3β in tumor tissue compared with adjacent nontumor tissue of WT mice." (PMID 37581937, 2023). "To confirm that NLRP12 expression is reduced explicitly in tumor epithelium, we isolated Ep-CAM+ cells from tumor and nontumor colon tissues of WT mice and measured NLRP12 at protein and RNA levels." (PMID 37581937, 2023). "Taken together, these findings suggest that higher activation of JNK in Nlrp12-/- HCC contributes to increased expression of cytokines and chemokines, which help recruitment of macrophages and dendritic cells in the tumor microenvironment, and tumor proliferation." (PMID 30990169, 2019). "NLRP12 is another potential therapeutic target, since NLRP12 knockout mice looks prone to colon inflammation and CRC, through enhanced activity of non-canonical NF-κB, ERK and AKT pathways, in both macrophages and tumor cells." (PMID 30837326, 2019). "Notably, the expression of STK38 was not affected by the absence of NLRP12 in the tumor epithelium, suggesting that NLRP12 regulates the Wnt/β-catenin pathway through its interaction with STK38 but not the regulation of STK38 expression." (PMID 37581937, 2023). "Consistent with the previous observation, there was a higher tumor burden and higher incidence of high-grade dysplasia and invasive adenocarcinoma; approximately 50% of Nlrp12–/– mice exhibited invasive adenocarcinoma, while no tumor invasiveness was observed in WT mice." (PMID 37581937, 2023). "Notably, inflammatory and proliferative molecules were not dysregulated in healthy Nlrp12-/- livers, indicating that NLRP12 suppresses those tumor-promoting mediators in the context of liver injury." (PMID 31941025, 2020). "Secondly, NLRP12 downregulates hepatocyte-specific expression of cytokines such as IL-6 and TNFα which promote proliferation and tumor growth, and chemokines CXCL1, CXCL2 and CCL2, which enhance inflammatory cell infiltration and thereby augment inflammation in the tumor milieu." (PMID 30990169, 2019). "To examine the role of NLRP12 in the regulation of JNK in non-parenchymal cells, such as Kupffer cells and hepatic stellate cells, in the tumor microenvironment, we isolated hepatocytes, Kupffer cells, and hepatic stellate cells from WT and Nlrp12-/- HCC tissues." (PMID 30990169, 2019).
cancer (19 papers, 2013 to 2025). A tumor composed of atypical neoplastic, often pleomorphic cells that invade other tissues. "NLRP12 deficiency promotes the proliferation and migration of cancer cells." (PMID 37581937, 2023). "However, NLRP12 was shown to influence the development of contact hypersensitivity and colitis associated cancer, which are both disease models with a strong innate immune system component." (PMID 23577168, 2013). "The present study explored the mechanism of NLRP12 in depth, broadening the scope and ideas for the regulation of cancer by the NLR family." (PMID 40796546, 2025). "Previous studies indicated that NLRP12 regulates cancer development via the NF-κB, ERK, p38, and JNK pathways." (PMID 37658975, 2023). "Since the Wnt/β-catenin pathway regulates genes involved in the invasion and migration of cancer cells, we quantitatively measured the role of NLRP12 in the migration capacity of MC38 cells." (PMID 37581937, 2023). "The NLR family (NLRP1, NLRP3, NLRC4, NLRP6, and NLRP12) and their binding partners have mixed roles in the pathogenesis of a variety of cancers." (PMID 33584697, 2020). "NLRP1, NLRP3, NLRC4, NLRP6, NLRP7, and NLRP12 have mixed roles in the pathogenesis of a variety of cancers as reviewed here in details." (PMID 33584697, 2020). "To understand an association of NLRP12 with human HCC, we analyzed publicly available cancer genomics databases." (PMID 30990169, 2019). "The NLR family member NLRP12 has recently emerged as a critical regulator of inflammation and cancer." (PMID 30990169, 2019). "The significance of NLRP12 in both chronic inflammation and cancer warrant extensive structure-function characterization of this protein and its mutants." (PMID 29293680, 2018). "As NLRP12 is a regulator of NF-κB, it would be beneficial to determine the role of NLRP12 in human cancer." (PMID 24273542, 2013). "We next wanted to examine the effect of NLRP12 on cancer cell proliferation and migration." (PMID 37581937, 2023). "Hence, our study strongly suggests that NLRP7, similar to NLRP3 and NLRP12, functions in an inflammasome-independent manner to facilitate cancer progression." (PMID 36980199, 2023). "Altogether, these findings strongly suggest that NLRP7, similar to NLRP3 and NLRP12, may function in an inflammasome-independent manner in cancer." (PMID 34203890, 2021). "The cancer genomics database suggests that NLRP12 is altered in about 2% of HCC patients." (PMID 31941025, 2020). "Moreover, NLRP12 also exerted a significant cancer-promoting effect in mouse models." (PMID 40796546, 2025). "We, therefore, wondered whether and how NLRP12 suppresses cancer invasiveness." (PMID 37581937, 2023). "Notably, like many other cancer-related genes, amplification of NLRP12 as seen in less than 0.5% HCC cases may also contribute to HCC." (PMID 30990169, 2019). "First, in terms of immune function, variations related to the nuclear factor kappa B (NF-κB) signaling pathway (NLRP12, TNIP2, IRAK4) and the autophagy process (TECPR1, ATG2A, SOGA1, TOM1) were identified in both carcinoma and sarcoma tumor groups." (PMID 40446009, 2025). "Therefore, NLRP12 may play a different role in different cancer types." (PMID 37658975, 2023). "As we compared the expression of NLRP12 in adenocarcinoma relative to adjacent nontumor tissue, NLRP12 expression was significantly reduced in most cancer samples (9/10) compared with that of adjacent nontumor colon tissue." (PMID 37581937, 2023). "Such combinatorial BM and non-BM derived roles for Nlrp12 have also been described in suppression of colon inflammation and cancer." (PMID 35313917, 2022). "Depletion of NLRP12 reduced TRAF3 levels, Together these results indicate that NLRP12 functions as a critical checkpoint molecule associated with cancer-related inflammation via regulation of non-canonical NFκB signaling." (PMID 34356615, 2021).
cancer (continued). "Although NLRP12 is not a classical cancer suppressor, our data suggest that genetic alteration or reduced expression of NLRP12 may facilitate tumorigenesis and cancer invasiveness." (PMID 37581937, 2023). "Although NLRP12 is not a major cancer suppressor gene, its expression and activation status may regulate HCC pathogenesis." (PMID 31941025, 2020). "The dimeric NLRP12 may modulate the noncanonical NF-κB signaling pathway and contribute to the induction of cancer." (PMID 29293680, 2018).
bacterial infection (8 papers, 2014 to 2025). "Both C57BL/6J and NLRP12-deficient mice have increased susceptibility to bacterial infection that correlates with defective neutrophil migration." (PMID 27779193, 2016). "Low expression of NLRP1 and NLRP12 might be related to a risk of susceptibility for bacterial diseases, via reduced cleavage of pro-IL-1β and pro-IL-18 to produce mature isoforms, and via avoidance of infected macrophage lysis which contributes to pathology in TB." (PMID 31821366, 2019). "The role of NLRP12 in immunity to bacterial infection is controversial as varied and contrasting results have been published using C57BL/6 mice." (PMID 27779193, 2016). "Given these markedly discrepant findings and postulated mechanisms of action of NLRP12 in bacterial infection, a closer examination is warranted." (PMID 27779193, 2016). "Our data emphasize the protective nature of NLRP10 against microbial pathogens, thus adding NLRP10 to the group of NLR family members such as NOD1, NOD2, NLRC4, NLRP3, and NLRP12 that initiate pro-inflammatory signaling to mediate host resistance toward bacterial infections." (PMID 29163529, 2017). "The role for NLRP12 in controlling bacterial infections is less clear." (PMID 27779193, 2016). "It was previously shown that in vitro knockdown of NLRP12 up-regulated IL-6 and TNF-α expression in bacterial infections, such as salmonella and Klebsiella pneumonia infection." (PMID 34956178, 2021). "An enhanced luminal level of lipocalin-2 that is primarily secreted by neutrophils was subsequently found in the absence of NLRP12 as early as day 8 after bacterial infection." (PMID 30559449, 2018).
inflammation (4 papers, 2012 to 2022). Aberrant reaction of the microcirculation characterized by movement of fluid and leukocytes from the blood into extravascular tissues. "Thus, it is possible that some additional negative regulators may function, either up-stream or down-stream, to compensate for the loss of NLRP12 activity during lung inflammation." (PMID 23577168, 2013). "In conclusion, the present study provides new insight into the immunoregulatory role of Nlrp12 in T cell-mediated CNS inflammation, triggered by different modes of immunological challenges (induced EAE and spEAE)." (PMID 30150571, 2018).
colorectal (3 papers, 2014 to 2019). "NLRP12 negatively regulates NF-κB and ERK in macrophages, dendritic cells, and T cells, and increased colorectal tumorigenesis in Nlrp12-/- mice is associated with higher activation of the NF-κB and ERK signaling pathways." (PMID 30990169, 2019).
infectious disease (3 papers, 2013 to 2024). A disorder directly resulting from the presence and activity of a microbial, viral, or parasitic agent in humans. "This study augments the growing body of research investigating the role of NLRP12 inflammasome in infectious diseases." (PMID 39119293, 2024). "The involvement of NLRP12 has been demonstrated in a variety of infectious diseases." (PMID 34956178, 2021). "While these initial studies were essential for the characterization of NLRP12, the physiological relevance of this NLR in infectious diseases is unclear." (PMID 23577168, 2013). "The role of NLRP12 in infectious diseases has not been extensively studied." (PMID 23577168, 2013).
autosomal dominant disease (2 papers, 2013 to 2023). Autosomal dominant form of disease. "This is an autosomal dominant disease caused by mutations in the NLRP12 gene encoding for the protein NLRP12 (or “monarch-1”), which plays a crucial role in immune system mechanisms against pathogenic agents." (PMID 24282415, 2013). "NLRP3-AID and NLRP12-AID are autosomal dominant disease and patients share similar phenotypes, including cold-induced urticaria/inflammatory disease and neurosensory hearing loss." (PMID 38343435, 2023).
adenocarcinoma (1 paper, 2023). A common cancer characterized by the presence of malignant glandular cells. "Adenocarcinoma tissue with a reduced level of NLRP12 compared with adjacent tissue exhibited significantly higher β-catenin and p-GSK3β." (PMID 37581937, 2023).
neurodevelopmental disorder (1 paper, 2026). A behavioral and cognitive disorder with onset during the developmental period that involves impaired or aberrant development of intellectual, motor, or social functions. "Exome sequencing identified two variants: one in the SETD1A gene, associated with neurodevelopmental disorders, and another in NLRP12, previously reported as benign." (PMID 42157874, 2026).
NLRP12 also shares sentences with these, for which no sentence is quoted: Blau syndrome (4 papers); antibody deficiency (3); atherosclerosis (3); acquired cold urticaria (2); chronic periodontitis (2); conjunctivitis (2); hereditary periodic fever syndrome (2); lupus nephritis (2); metabolic disease (2); Muckle-Wells syndrome (2); multiple sclerosis (2); Myalgia (2); Aicardi-Goutières syndrome (1); Allergy (1); autoimmune lymphoproliferative syndrome (1); autoimmune uveitis (1); C3 glomerulopathy (1); chronic granulomatous disease (1); coinfection (1); colorectal adenoma (1); Familial cold urticaria (1); Fever (1); generalized pustular psoriasis (1); glaucoma (1); Heat Stroke (1); hyperuricemia (1); influenza (1); injury (1); juvenile idiopathic arthritis (1); leukocytosis (1).
A further 24 diseases each share a sentence with NLRP12 in 1 paper.